PARP1 (poly(ADP-ribose) polymerase 1)
Diseases named in the same sentence as PARP1 in open-access papers (continued):
Sharing a sentence is not in itself a finding about the gene and the disease.
cancer (continued). "PARP1 accumulation mediated by TRIP12 dysfunction sensitizes BRCA-proficient cancer cells to PARP inhibitors through increased PARP1 trapping." (PMID 38201233, 2023). "Poly ADP‐ribose polymerase 1 (PARP‐1) recognizes single‐strand breaks in DNA and repairs them, and inhibition of PARP‐1 leads to decreased DNA damage repair and causes apoptosis in cancer cells." (PMID 37070530, 2023). "More generally, defects in each of the players of the LoL-DDR response described here (NF-κB, PARP1, FOXO1, DUOX1 and DUOX2) share common phenotypes, such as defects in cell homeostasis and metabolism, aging and cancer predisposition." (PMID 36869180, 2023). "Other pre-clinical cancer studies also demonstrated that the inhibition of PARP-1/2 retained NK cell viability and primed tumor cells to NK-cell-mediated killing in various cancer models, such as breast, prostate, NSLC, and chronic myeloid leukemia." (PMID 36829496, 2023). "In the case of the remaining cancer lines, depending on the derivative used, PARP1 degradation ranged between 25% and 50%." (PMID 37175377, 2023). "Compounds 2a–3c (at IC50 concentration for individual lines) are able to inhibit PARP1 activity and support its degradation in cancer cells." (PMID 37175377, 2023). "PARP1 overexpression and PARP1 inhibitors as possible therapies have been reported in numerous cancers, putting forward PARP1 as a potential biomarker implicated in the development of pSS." (PMID 37176092, 2023). "Our findings indicate the functional activation of effector caspases in both cell lines and are consistent with previous research, showing iodine-induced proteolytic cleavage of PARP1 in MCF-7 cancer cells." (PMID 37373017, 2023). "More recently, PARP-1 was also demonstrated to play a central role in PARthanatos observed in cancer cell lines following treatment with the alkylating agents MNNG and MMS, which was dependent on the MGMT level." (PMID 36902118, 2023). "Our findings indicate that the level of PARP1 degradation probably depends inter alia on the type of cancer cell and its individual characteristics, and its expression of individual genes or protein activity." (PMID 37175377, 2023). "Image-based drug screening of ALL cells co-cultured with MSC demonstrated high cytotoxic specificity of PARP1/2 inhibitors for ALL relative to non-cancer BMSC samples, as determined by IC50 values for each sample." (PMID 37989729, 2023). "It is worth noting that the same compound yielded very different levels of PARP1 degradation activity between cancer lines." (PMID 37175377, 2023). "Although PARP1 inhibitors are primarily used in the clinic to treat cancers with an impaired homologous recombination signaling pathway (especially BRCA1 mutation), they have recently been used as part of an adjunctive therapy in other solid cancers." (PMID 37509303, 2023). "The role of PARP1 and PARP2 in the DNA damage response underscores the potential of targeting these pathways in cancer therapy, particularly in the context of BRCA-deficient cancers." (PMID 38111536, 2023). "Nimbolide inhibits RNF114 to induce PARP1 trapping, and its analogs hold promise as therapeutic agents for BRCAmut cancers." (PMID 37878693, 2023). "AF-mediated generation of ROS and subsequent DNA damage activates the enzyme poly(ADP-ribose) polymerase-1 (PARP) in multiple cancer types." (PMID 36978917, 2023). "In future studies, we will assess the pharmacological inhibition of USP1 and/or PARP1 as anti-cancer compounds for CCA." (PMID 37821462, 2023). "Since PARP-1 is overexpressed in a multitude of cancers, this therapeutic approach has the prospective to be extrapolated to other cancers as well." (PMID 36834491, 2023). "Of note, the blockage of PARP1 activity that inhibits the repair of DNA damages in tumor cells is a promising approach for cancer treatment." (PMID 36077699, 2022).
cancer (continued). "Due to the crucial roles in many cellular procedures, PARP1 has been considered as a therapeutic target for the potential treatment of cancers." (PMID 36257929, 2022). "Next, we considered the relationship among PARP1 and interferon-stimulated genes (ISGs) at the transcriptional level in cancer patients by analyzing the transcriptome profiles in The Cancer Genome Atlas (TCGA) database." (PMID 36624848, 2022). "The roles of PARP1 in EMT in cancer have been investigated in a range of cancer types and the effects of PARPi also remain controversial." (PMID 35173550, 2022). "Our group has successfully demonstrated that the simultaneous targeting of PARP1 and RAD52 induces “dual synthetic lethality” in BRCA1/2-deficient cancer cells." (PMID 36497275, 2022). "PARP1/2 as plausible therapeutic targets have attracted considerable interests, and multitudes of PARP1/2 inhibitors have emerged for treating cancer, metabolic, inflammatory, and neurological disorders." (PMID 36438061, 2022). "These compounds can provide new scaffolds for developing novel PARP-1 inhibitors applicable to cancer therapy using further hit-to-lead structural modification strategies." (PMID 36353483, 2022). "Owing to its functions in promoting cell stability and survival, PARP1 is considered to contribute to the immune evasion and drug resistance of cancer cells." (PMID 36091054, 2022). "Second, a combination of OXPHOS and glycolysis inhibitors induced parthanatos in cancer cells, a process mediated by PARP1 that affects mitochondrial activity, likely via NAD depletion." (PMID 36428689, 2022). "EZH2 inhibitors reduces proliferation of BAP1-mutant mesothelioma cell lines, while platinum-based drugs and PARP-1 inhibitors should be able to target cancer cells with defective DNA repair mechanisms." (PMID 36318367, 2022). "In particular, PARP1 has been extensively studied in various cancer types, with a focus towards PARP1 inhibitors and synthetic lethality." (PMID 34319003, 2022). "PARP1 inhibitors have been shown to sensitize cancer cells to other anticancer drugs and hence being used to overcome drug resistance of aggressive tumors." (PMID 36172283, 2022). "The discovery of synthetic lethality as a result of the combined loss of PARP1 and BRCA has revolutionized the treatment of DNA repair-deficient cancers." (PMID 36568963, 2022). "[18F]WC-DZ-F was tested as a PET imaging agent for measuring PARP1 levels in prostate and other types of cancers." (PMID 36438061, 2022). "The enzyme PARP1 emerged as an attractive target for cancer therapy, being involved in DNA repair processes." (PMID 35897968, 2022). "An in vitro study using human cancer cells with BRCA1/2 deficiency demonstrated that chemically-mediated or shRNA-mediated PARG inhibition resulted in increased PAR and decreased PARP1 trapping, as well as increased resistance to PARPi." (PMID 35626108, 2022). "Therapeutic approaches have been suggested for the treatment of BAP1-deficient cancers such as the epigenetic drugs that inhibit EZH2, ther platinum-based compounds and PARP-1 inhibitors." (PMID 36318367, 2022). "Unfortunately, there are several mechanisms by which cancer cells can develop resistance, attenuating the effect of PARP1 inhibition." (PMID 36232374, 2022). "Recent studies reported that PARP1 plays a very extensive role in regulating the occurrence and development of tumors, not only participating in cancer cell proliferation, but also participating in metastasis." (PMID 36566215, 2022). "Inhibition of PARP1 has been proven to enhance the cytotoxicity of DNA-damaging agents in cancer treatments." (PMID 35847980, 2022). "Considering that Dasatinib and PARP1 inhibitors have been reported in IDH1/2 mutant ICC or other cancers 54-56, we tested the effect of JQ1 and Vorinostat on clone formation ability in four ICC cell lines." (PMID 34987644, 2022). "PARP1 inhibitors have been approved as drugs to treat various cancers in clinics, based on its role in DNA repair." (PMID 36077699, 2022).
cancer (continued). "The effectiveness of PARPi in cancer treatment relies on their ability to trap PARP1 in the chromatin." (PMID 35013556, 2022). "Strikingly, CM-challenged cancer cells had lower caspase-3 processing into the active p17 and p19 fragments, whereas PARP-1 cleavage followed the same pattern." (PMID 35256052, 2022). "In clinical settings, PARP-1/2 inhibitors are currently being used for the treatment of certain cancer types, namely ovarian and breast cancer." (PMID 35740560, 2022). "The synthesized compounds were evaluated in the in the PARP1 enzyme inhibitory screening, cancer cell based antiproliferative assay, cell cycle arrest and apoptosis studies." (PMID 36699082, 2022). "BER factors, including PARP1, POL β, and XRCC1, are frequently dysregulated in cancers and associated with poor survival outcomes." (PMID 35457130, 2022). "Olaparib (Ola) and Talazoparib (Tala) were two Food and Drug Administration (FDA) approved canonical PARP1 inhibitors that recommended for the treatment of various cancers." (PMID 35178387, 2022). "PARP1 directly or indirectly interacts with diverse oncogenic proteins or transcription factors, thus salvaging cancer cells from apoptosis and further modulating carcinogenesis." (PMID 35100974, 2022). "PARP1 mRNA levels are upregulated in several cancer types, including HCC; however, the expression of PARP1 protein did not parallel these changes in all the tissue panels examined." (PMID 35954469, 2022). "Firstly, we identified associations of exposure of SBS-CL1 with sensitivity toward PARP inhibitors olaparib, rucaparib, veliparib, and PARP1 gene k.o., observed across three cancer types." (PMID 35614096, 2022). "The synthesized molecules were evaluated using PARP1 enzyme inhibitory screening and cancer cell-based antiproliferative assays and apoptosis studies." (PMID 36699082, 2022). "We find it very interesting, although the mechanisms are not well understood, that the PARP1 gene, which is a target of miR-519a-3p, along with miR-519a-3p itself, can express in the same direction in some cancers and in opposite ways in PD." (PMID 35741059, 2022). "The enzyme PARP1 is an attractive target for cancer therapy, as it is involved in DNA repair processes." (PMID 35897968, 2022). "Recent studies have shown that PARP1 can promote cancer progression through impacting on DNA repair, apoptosis inhibition, and maintaining the activity of the MAPK signaling pathway." (PMID 35739271, 2022). "In particular, PARP1- and PARP2-specific inhibitors are being used in combination with conventional anticancer drugs to promote synthetic lethality in cancer cells with BRCA1/2 mutations." (PMID 35269974, 2022). "When excessive DNA damage occurs, PARP-1 can regulate apoptosis in cancer cells by changing the activity and localization of cytoplasmic proteins like apoptosis-inducing factor." (PMID 35372044, 2022). "These compounds were shown to possess anticancer activity that was mediated through targeting mortalin and PARP1 proteins, essential for cancer cell survival and proliferation." (PMID 36172283, 2022). "Astatine-211-parthanatine ([211At]PTT) is an alpha-emitting radiopharmaceutical therapeutic that targets poly(adenosine-diphosphate-ribose) polymerase 1 (PARP1) in cancer cells." (PMID 36396952, 2022). "Currently some PARP-1 inhibitors, including olaparib, rucaparib and niraparib, are approved as a therapy for several cancer types due to their synthetic lethality mechanism." (PMID 35455964, 2022). "It was shown in numerous reports that many cancer cells exhibit high level of PARP1 and pADPr, which is frequently cooperate with lower PARG level." (PMID 35585513, 2022).
cancer (continued). "Mutations in PARP1 that prevent PARP1 trapping cause profound PARPi resistance in pre‐clinical in vitro and in vivo models of BRCA1 mutant cancer and have been seen in a single case of clinical PARPi resistance." (PMID 35567571, 2022). "PARP-1 inhibition has been reported to sensitise cancer cells to various forms of ionising radiation including conventional gamma irradiation, proton-beam irradiation and radionuclide therapy." (PMID 36106115, 2022). "Accordingly, anti-cancer drug and catalytic inhibitor of PARP1 olaparib strongly represses PARP1-dependent transcription in vitro." (PMID 35806109, 2022). "Their high selectivity, oral availability, pharmacokinetic and pharmacodynamic properties, and potency make PARP-1 inhibitors attractive for multiple cancers that share high levels of replication and genomic instability." (PMID 35158955, 2022). "PARPi-FL is a fluorescent nuclear marker, specific for the PARP1 DNA repair enzymes that are differentially overexpressed in oral pre-cancers and cancers." (PMID 35478042, 2022). "To assess the effect of the treatment on the apoptosis of cancer cells, we performed IF for cleaved caspase-3 and cleaved PARP1." (PMID 35109895, 2022). "Small-molecule PARP1 inhibitors, such as niraparib, rucaparib and olaparib, have been developed to treat cancers." (PMID 35410300, 2022). "The immunomodulatory functions of PARP-1 inhibitors (PARPi) in cancers and inflammatory diseases have attracted increasing attention." (PMID 36146855, 2022). "In parallel to the successful clinical implementation of PARP1/2 inhibitors as anti-cancer drugs, which interfere with the DNA repair machinery, these small molecule agents have also gained attention as vehicles for molecular imaging and radiotherapy." (PMID 35267438, 2022). "We examined PARP1 mRNA expression in matched pan-cancer tumor tissues in the TCGA database and found that PARP1 mRNA expression was elevated in 14 types of cancers (e." (PMID 36203459, 2022). "The use of molecules, such as olaparib, niparib, or iniparib, inhibit PARP1 preventing the repair of possible breaks in the DNA double strand, affecting the vitality and replication of the cancer cells." (PMID 36232374, 2022). "In 2000s, the scientific focus on PARP1 transitioned from validating its molecular functions to identifying its physiological and pathological role in human cancer." (PMID 36284291, 2022). "These inhibitors have been used for exploring the therapeutic potentials and mechanistic actions of PARP1‐mediated PARylation in various cancer cells and neurological conditions including MS as discussed in the following sections." (PMID 34935305, 2022). "A PARP1 inhibitor was first successfully used as monotherapy based on the concept of “synthetic lethal therapy” for the treatment of cancers exhibiting intrinsic DNA repair anomalies." (PMID 35422863, 2022). "In the context of cancer remediation, the impact of DNA methylation and PARP1 pharmacological inhibitors, and their relevance as a combination therapy are highlighted." (PMID 35327610, 2022). "This is likely due to the fact that all the PARP‐1 inhibitors approved to date for the treatment of cancer act by trapping PARP‐1 on DNA thereby inhibiting homologous DNA repair." (PMID 36125899, 2022). "This is consistent with compensatory action of Lig3 in replication context in case of Lig145 and with one of the previous reports on the role of Parp1 obtained in a human cancer cell line HEK29346,47." (PMID 35701408, 2022). "The rationale behind the use of PARP inhibitors for SCLC derives from the high expression of PARP1 in these cancer cells." (PMID 35716328, 2022). "As a DNA damage sensor and signal transducer, PARP1 is activated by DNA breaks and participates in their repair, playing a critical role in the survival of cancer cells and influencing platinum sensitivity." (PMID 35875162, 2022). "Numerous studies have shown up-regulation of PARP-1 expression in cancer cell lines and patients’ tissues." (PMID 35406503, 2022).
cancer (continued). "The different layers of regulation that PARP-1 activity exerts on histone/DNA epigenetic modifications are certainly involved in the success or failure of PARPi in cancer therapy." (PMID 36612003, 2022). "Compound 11l had powerful inhibiting effects on Topo and PARP-1 as well as a considerable inhibitory effect on cancer cell proliferation." (PMID 36615391, 2022). "Cotreatment with PARP1 inhibitors and conventional chemotherapeutics was shown to highly enhance the efficacy of chemotherapy that exerts cancer suppressive effects at reduced doses." (PMID 35422863, 2022). "The usage of PARPi, which predominantly blocks the activity of PARP1, PARP2 and PARP3, is a well-established example of synthetic lethality-based therapy in BRCA1/2-mutated cancers with a limited toxicity towards normal cells and tissues." (PMID 36497275, 2022). "Therapies targeting the enzyme, PARP-1, have since established their place as maintenance drugs for cancer." (PMID 35158955, 2022). "Secondly, PARP-1 inhibitors prevent auto-PARylation and consequently the release of PARP-1, downregulating PARP-1 levels and thus reducing DNA repair in cancer cells." (PMID 35158955, 2022). "The capacity to assess the PARP-1 status in a target cancer cell is emerging as a means to select patients for and to monitor PARP-1 inhibitor therapy." (PMID 35906379, 2022). "Taken together, we discover two novel anti-tumor compounds that target PARP-1 with an induced autophagy process and provide potential hit compounds for the anti-cancer drug development." (PMID 36353483, 2022). "Among the derived molecules, an olaparib–chlorambucil hybrid molecule (C2) exhibited high potency in the inhibition of PARP1 activity and showed high antiproliferative activity against a group of cancer lines." (PMID 36699082, 2022). "In silico studies of the influence of the studied compounds on PARP1 were confirmed in vitro with the use of eight cancer cell lines." (PMID 35682740, 2022). "Based on these findings, PARP1 became the attractive therapeutic target for the treatment of cancer." (PMID 36284291, 2022). "Subsequently, it was found that inhibition of PARP1 led to an improvement in inflammatory disorders via suppression of NF-κB and that PARPi were a means of targeting cancer cell apoptosis through their effect on the NF-κB signaling pathway in HCC." (PMID 35954469, 2022). "Polθ is becoming a new target in cancer research because it demonstrates numerous synthetically lethal interactions with other DNA repair mechanisms, e.g., those involving PARP1, BRCA1/2, DNA-PK, ATR." (PMID 36613762, 2022). "Anti-cancer drug and PARP1 catalytic inhibitor olaparib strongly represses PARP1-dependent transcription." (PMID 35806109, 2022). "Recently, PARP1/2 inhibitors have been reported to be involved in cancer immunity via various mechanisms." (PMID 35910366, 2022). "Activated by DNA interruptions through ultraviolet (UV) exposure, PARylation is synthesized by PARP1 and serves as a survival mechanism for cancer and metabolic diseases." (PMID 35998296, 2022). "Parthanatos is closely related to cancer, mainly because PARP1 plays an important role in the occurrence, development, and treatment of tumors." (PMID 35359956, 2022). "They used the CRISPR/Cas9-loaded exosomes to suppress the expression of poly (ADP-ribose) polymerase-1 (PARP-1), which was closely related to the repair of chemotherapy-induced DNA damage in cancer cells." (PMID 35292030, 2022). "Niraparib (MK-4827) is an orally bioavailable PARP1/2 inhibitor, also showing cancer cytotoxicity levels comparable to olaparib." (PMID 35065680, 2022). "Another study found that orphan snoRNA SNORA73 inhibits PARP1 auto-PARylation to affect cancer genome stability by forming a small nucleolar ribonucleoprotein with PARP1 and DKC1/NHP2." (PMID 35552378, 2022).